IL10 (interleukin 10)
Diseases named in the same sentence as IL10 in open-access papers (continued):
Sharing a sentence is not in itself a finding about the gene and the disease.
periodontitis (continued). "Our finding of elevated IL-10 levels may reflect a compensatory mechanism in periodontally healthy patients, as our strict inclusion criteria eliminated periodontitis-related inflammation, potentially amplifying the role of IL-10 in counteracting proinflammatory cytokines." (PMID 40959363, 2025). "Additionally, periodontal ligament stem cells (PDLSCs) should be used as a control in future experiments to determine whether IL‐10‐MSCs can replace PDLSCs in terms of efficacy in the treatment of periodontitis." (PMID 41181974, 2025). "In non-smokers, increased level of IL-10 may occur as a consequence of increased BI and the association is most likely related to progression and/or recurrence of periodontitis during step IV therapy." (PMID 38627806, 2024). "Consequently, low IL-10 levels lead to the inadequate suppression of pro-inflammatory cytokines and collagenases, adversely affecting bone structure in conditions such as osteoporosis and periodontitis." (PMID 39336814, 2024). "In addition, higher levels of IL-10 were observed in the gingival crevicular fluid and in the inflamed tissue of periodontitis patients along with the presence of putative IL-10-producing cells, such as CD4+CD25+FoxP3+ regulatory T cells, in the inflammatory infiltrate of gingival tissues." (PMID 39253090, 2024). "Notably, only IL10 has been linked to immunosuppression, indicating that the IFNβ-ISG15-IL10 axis might promote an anti-inflammatory response in periodontitis through IL10 expression." (PMID 37876725, 2023). "Hence, IL-10 is considered to be a potential mediator of bone homeostasis for periodontitis." (PMID 35248085, 2022). "Therefore, we aimed to test the hypothesis that LPS-induced periodontitis could contribute to peripheral changes of inflammatory biomarkers (IL-6, IL-10, PTX3, and sTWEAK) in rats." (PMID 31583485, 2020). "Periodontitis has been shown to be associated with a raised serum pro-inflammatory state as shown by increases in C Reactive Protein (CRP) and pro-inflammatory cytokines (e.g. Tumour Necrosis Factor α (TNFα)) with a reduction in anti-inflammatory markers (e.g. interleukin 10 (IL 10))." (PMID 26963387, 2016). "Herein, the human IL10 gene was transfected into human MSCs to create an IL10 overexpressing stable MSC strain and then used for the first time in a rat periodontitis model to assess its therapeutic effect and investigate its mechanism." (PMID 41181974, 2025). "In gingival tissues from patients with periodontitis, an increased proportion of macrophages and elevated expression levels of IFNβ, ISG15, and IL-10 were observed." (PMID 39669221, 2025). "The balance between TGF-β, IL-10, and TNF-α plays a key role in healing, suggesting that PRF therapy supports tissue repair and inflammation control in periodontitis patients." (PMID 40710037, 2025). "This led to the following research question: What is the effect of closed-field scaling and root planning on serum levels of IL-1β, IL-4, IL-6, IL-8, IL-10, IL-12p70, IL-17A, VEGF, and TNF-α in patients with periodontitis and high blood pressure?" (PMID 40002786, 2025). "In the first part of the study, we examined the effect of adiponectin on the expression in periodontal ligament cells of mRNA of mediators involved in periodontitis pathogenesis (TNF-α, IL-1, IL-6, IL-8, IL-10, IL-17, IL-18)." (PMID 40282186, 2025). "The aim of this study was to investigate the relationship between the severity of apical periodontitis (AP) and chronic periodontitis (CP) and serum (s) TNF-α, IL-10, PGE2 and NO levels, as well as PGE2 and NO levels in gingival crevicular fluid (GCF) samples." (PMID 38795217, 2024). "In turn, neutrophils isolated from periodontitis were characterised by high expression of CHD1 and JMJD2A, which corresponds with the in vitro model of neutrophils exposed to IL-10." (PMID 38745328, 2024).
periodontitis (continued). "The systemic inflammatory–oxidative effects of periodontitis and MetS were biochemically evaluated using the serum TNF-α level, IL-1β/IL-10 ratio, and oxidative stress index (OSI: TOS/TAS)." (PMID 39590401, 2024). "The anti-inflammatory cytokines of IL-10, TGF-β and IL-11, downregulate the expression levels of pro-inflammatory factors, protect the periodontium and inhibit the development of periodontitis." (PMID 38178140, 2024). "The hub genes identified in the periodontitis comorbidity network, such as TNF, IL6, PTGS2, IL10, and NOS3, play pivotal roles in connecting periodontitis with various systemic diseases, as indicated by their high connectivity degrees." (PMID 39337647, 2024). "Single-cell analysis was conducted on the gingival tissues of patients with periodontitis, which revealed a higher proportion of macrophages in the periodontitis-diseased tissue and increased expression of IFNβ, ISG15, and IL10." (PMID 37876725, 2023). "According to certain research, the progression of periodontitis is characterized by high concentrations of the pro-inflammatory cytokines, IL1 and TNFα, and low concentrations of IL10 and transforming growth factor β." (PMID 37570272, 2023). "IL-10 levels in GCF (pg/site) were 127.20 (35.76) pg, 50.76 (28.74) pg and 13.49 (14.04) pg for healthy, Stage I-II and Stage III-IV periodontitis groups, respectively." (PMID 37246231, 2023). "In contrast, patients with aggressive periodontitis were found to have lower levels of other cytokines, including CCL2, M-CSF, GM-CSF, IL-1ra, IL-10, and IL-13." (PMID 38139161, 2023). "In the periodontitis group, macrophages were observed to exhibit elevated expressions of TLR4, IFNAR1 (the receptor of IFNβ), ISG15, ITGB2 (the receptor of ISG15), IL10." (PMID 37876725, 2023). "A mucoadhesive gingival patch with nano-emulsion of mangosteen rind extract has the potential to treat periodontitis by decreasing TNF-α, RANKL, and increasing IL-10 expression." (PMID 36050950, 2022). "For example, we need to identify the precise effects of MOP-EGCG on other markers of periodontitis such as TNF-α and IL-10." (PMID 36212598, 2022). "After classifying the severity of the periodontitis among participants it was observed that the levels of cytokines such as IFN-γ, IL-10 and TNF-α were elevated in PD." (PMID 35055157, 2022). "Meanwhile, the results of this study confirm that nano-emulsion of mangosteen rind extract in a mucoadhesive gingival patch plays a role in periodontitis, where TNF-α, IL-10, and RANKL expression are the main indicators of periodontitis." (PMID 36050950, 2022). "The present study analyzed salivary levels of IL-1β, IL-6, MMP-8, and IL-10 in periodontally healthy subjects and stage III periodontitis individuals." (PMID 35368315, 2022). "This study showed that topical application of a mucosal adhesive gingival patch loaded with nano-emulsion of mangosteen rind extract has therapeutic potential in periodontitis by decreasing the expression of TNF-α and RANKL and increasing IL-10 expression." (PMID 36050950, 2022). "High levels of IL-17A, IL-17F IL-22, IL-25, IL-33, IL-10 and INF-y were found in gingival biopsies compared with intestinal biopsies from patients with IBD and periodontitis." (PMID 34501547, 2021). "In the chronic phase of periodontitis, CD4+ T lymphocytes differentiate towards an anti-inflammatory Th2 profile, characterized by the production of IL-4, IL-5, IL-6, and IL-10." (PMID 34707462, 2021). "There were also detectable levels of other inflammatory mediators such as TGF-β1, IL-1β, IL-2, IL-4, IL-10, IL-12p70, and IL-17A in the GCF samples of periodontitis patients." (PMID 34502071, 2021). "Taken together, our findings suggest that decitabine inhibits bone resorption in mice with periodontitis by upregulating KLF2 expression and thereby enhancing the expression of IL10 and TGFβ1." (PMID 33671221, 2021).
periodontitis (continued). "All of these results show that SPRC alleviated the progression of periodontitis by inhibiting proinflammatory cytokine (IL-17 and IL-6) expression and promoting anti-inflammatory cytokine (IL-10 and TGF-β) expression in a rat periodontitis model." (PMID 35087796, 2021). "Thus, IL-10 could be a therapeutic strategy in periodontitis." (PMID 33803774, 2021). "Rats with periodontitis (group 3) expressed significantly higher immunoreactivities of IL-6 and TNF-α and lower IL-10 immunoreactivity compared to those other groups (p<0.05)." (PMID 34586188, 2021). "Macrophage polarization toward a higher M1/M2 ratio was shown to be involved in the progression of gingivitis to periodontitis, with sustained IL-1β, IL-6, and TNF-α and diminished IL-10 expression." (PMID 34063147, 2021). "Anti‐inflammatory cytokines IL‐4 and IL‐10 have been shown to be lower, or the same, in GCF in RA patients and periodontitis patients than in periodontally healthy controls." (PMID 33954982, 2021). "In active lesions in patients with periodontitis, Foxp3 mRNA was significantly overexpressed compared to inactive lesions, while TGF-β and IL-10 expression were downregulated in active periodontal lesions." (PMID 33149125, 2020). "Significantly higher levels of serum of cytokines IL-6, TNF-α and IL-1β, IL10, IL35, and TGF-β1 were measured in patients with chronic periodontitis when compared to the healthy control group." (PMID 32604936, 2020). "Several studies have also suggested that upregulated IL‐10 and TGF‐β are found in periodontitis but IL‐17 was downregulated in the PH group compared with the CP group." (PMID 31944625, 2019). "Thus, cross sectional studies have shown that the presence of periodontitis, or antibodies to common periodontal bacterial flora, are associated with an increase in a systemic proinflammatory state characterized by an increase in serum CRP; TNFα and TNFα/IL10 ratios in participants with AD." (PMID 26963387, 2016). "A panel of 8 SNPs in VEGF, ACT, HMG-CR, INF-γ, IL-1β, IL-10, IL-6 and TNF-α genes in patients with periodontitis and controls (CTR) was studied and genotype distributions and allele frequencies were obtained." (PMID 24274085, 2013). "The aim of this study is to compare genotypes and soluble protein of pro and anti-inflammatory cytokines (IL-1α, IL-1β, IL-6, IFN-γ, IL-10, TNF-α and IL-4) in subjects with or free of chronic periodontitis." (PMID 23046796, 2012). "Out of the most studied genes in aggressive periodontitis [IL1-A and IL1-B (2q14), IL-4 (5q31.1), IL-10 (1q31-q32), FcγRIIa, FcγRIIb, and FcγRIIIb (1q23), and TNFA (6p21.3)], IL-4 and TNFA map in the intervals with suggestive association results." (PMID 20383335, 2010). "Periodontitis triggers a robust immune response, including elevated pro-inflammatory cytokines, increased serum C-reactive protein (CRP), and reduced anti-inflammatory markers such as interleukin-10." (PMID 40038641, 2025). "Macrophage polarization critically influences periodontitis progression: pro-inflammatory M1 macrophages exacerbate bone resorption through IL-6 and TNF-α secretion, whereas anti-inflammatory M2 macrophages facilitate tissue repair via cytokines such as IL-10." (PMID 41124423, 2025). "Notably, FAPi treatment also enhanced the expression of macrophage repair–related genes, such as IL‐10 and TGF‐β, fostering a pro‐regenerative environment in periodontitis." (PMID 39716898, 2025). "Immunofluorescence further demonstrated that macrophage polarization in vivo shifted in response to therapy: periodontitis lesions were dominated by M1 macrophages (high CD86 and IL‐1β, low CD206 and IL‐10), whereas HIPPE‐QU treatment skewed macrophages toward the M2 phenotype." (PMID 41020683, 2025). "The importance of IL-10 and -17 in the pathogenesis of periodontitis has recently been reviewed and will therefore not be covered in this review." (PMID 41289041, 2025).
periodontitis (continued). "The importance of IL-10 and IL-17 in the pathogenesis of periodontitis has recently been reviewed and will therefore not be covered in this review." (PMID 41289041, 2025). "Numerous studies have confirmed that individuals with periodontitis exhibit higher serum levels of inflammatory markers such as IL-1β, TNF-α, IL-17A, IL-6, and lower levels of the anti-inflammatory cytokine IL-10 compared to healthy controls." (PMID 40732209, 2025). "Significant reductions in gingival crevicular fluid (GCF) TNF-α and IL-10 levels have been observed following non-surgical periodontal therapy (NSPT) in Stage III Grade B periodontitis." (PMID 41440349, 2025). "Conversely, IFN-γ, IL-4, IL-6, IL-10, and IL-12p70 exhibited no statistically significant changes across healthy, gingivitis, and periodontitis sites." (PMID 41303313, 2025). "Various studies have reported that salivary IL-10 concentrations in individuals with periodontitis increase, decrease, or do not differ compare to healthy controls." (PMID 39964474, 2025). "In the periodontitis group, IL-10 was not correlated with the clinical periodontal parameters, whereas IL-12 was moderately positively correlated with PD, LPD, and LCAL." (PMID 39080003, 2024). "Additionally, periodontal tissue affected by periodontitis showed an increase in the M1 inflammatory factors TNF-α and IL-1β as well as the M2 inflammatory factor IL-10." (PMID 38347915, 2024). "Although IL-10 concentrations increased in the experimental periodontitis groups in our study, this increase was not statistically significant." (PMID 38359268, 2024). "In contrast, ex-vivo cell cultures show that smokers with periodontitis express a lower IL-10 level than non-smokers." (PMID 38627806, 2024). "This activation of the cellular IL-10/IL-10R pathway promotes the osteogenic differentiation of BMSCs, inhibits the differentiation of BMDM osteoclasts, and decreases alveolar bone resorption in periodontitis." (PMID 38907216, 2024). "We assessed the levels of Interleukin-10 (IL-10), Interleukin-12 (IL-12), and Interleukin-18 (IL-18) in the gingival crevicular fluid (GCF) of subjects with advanced periodontitis (SIII-SIV) compared to healthy controls and evaluated their correlations with clinical measurements." (PMID 39080003, 2024). "IL-6 and IL-8 were significantly upregulated, and IL-10 was downregulated in the periodontitis group compared to the non-periodontitis group." (PMID 39697803, 2023). "Also, in a mouse model of hyperlipidemia with periodontitis, GMSCs significantly reduce the serum levels of pro-inflammatory cytokines IL-6 and TNF-α, while increasing the anti-inflammatory cytokine IL-10 and improving periodontal tissue regeneration." (PMID 37626831, 2023). "EXO-NET EVs display increased IL-6, IL-8, and IL-1β in periodontitis individuals compared to those without, with significantly reduced IL-10 expression." (PMID 39697803, 2023). "Moreover, the study found that in the chronic periodontitis group of T2DM, there was a significant difference in the serum level of miR-200b, which was significantly negatively correlated with IL-10 and positively correlated with TNF-α." (PMID 37664859, 2023). "On the other hand, anti-inflammatory cytokines IL-4 and IL-10 showed a negative correlation with periodontitis." (PMID 37246231, 2023). "Unlike the other 3 genes, it is specifically the alternate SNPs, (A) allele of IL1B-511 and (C) allele of IL10-1082, that promote strong GCF exudation, efficient bacterial removal from the crevice and mild or no periodontitis." (PMID 37762554, 2023). "Unlike antimicrobial peptide LL-37 and IL-6, IL-4 and IL-10 levels in GCF were substantially lower in the periodontitis groups as compared to healthy individuals at baseline." (PMID 37246231, 2023).
periodontitis (continued). "It is also found that macrophage phenotype transitions in periodontitis involve the release of higher levels of IFNβ, ISG15, and IL10 by the anti-inflammatory M2 macrophage phenotype compared to the pro-inflammatory M1 phenotype and myeloid-derived suppressor cells (MDSCs)." (PMID 37876725, 2023). "We noted a similar pattern of mediators released by non-stimulated periodontitis neutrophils and their gene expression, and neutrophils isolated from healthy volunteers stimulated in vitro by IL-10." (PMID 35757755, 2022). "The plasma concentration was not investigated in this study, but the overexpression of IL-10 in the IBD patients did not allow any conclusion to be drawn regarding the possible occurrence of periodontitis in IBD patients." (PMID 34383142, 2022). "Hence, this study investigated the therapeutic potential of nano-emulsion of mangosteen rind extract in a mucoadhesive gingival patch on a periodontitis model induced by P. gingivalis and its effect on TNF-α, IL-10, and RANKL expression." (PMID 36050950, 2022). "Consequently, a high expression profile involving proinflammatory cytokines, IL‐1, IL‐7, IL‐10, IL‐17, IL‐8, TNF‐α, and monocyte chemoattractant protein‐1, were detected both in patients with periodontitis and those with COVID‐19." (PMID 35578891, 2022). "At the site of periodontitis, the levels of proinflammatory cytokines such as TNF-α, IFN-γ, IL-1, IL-6, IL-12 and G-CSF are significantly increased while anti-inflammatory cytokines are decreased (IL-4 and IL-10)." (PMID 34868054, 2021). "To compare PIL landscape-based risk classification with traditional biomarkers for periodontitis, we performed a head-to-head comparison and found that the protein levels of IL-1β, MMP-9, and IL-10 in the PICF do not predict peri-implantitis outcomes." (PMID 34093848, 2021). "In addition, periodontitis reduced IL-6, MCP-1, granulocyte-macrophage colony-stimulating factor, and interferon-γ (IFN-γ) expression in the brains of WT mice and reduced IL-10 expression in 5xFAD mice." (PMID 34445604, 2021). "A subset of B-regs (B regulatory cells), B10, has been found in gingival tissues of patients with and without periodontitis, and has been suggested to play anti-inflammatory and anti-bone resorbing functions due its ability to secrete IL-10." (PMID 34594237, 2021). "Interestingly, maximal expression of Treg-related genes Foxp3, IL-2, IL-10, CTLA-4, CD25, and GITR was reached later than Th17-related genes, on day 15 post-periodontitis induction." (PMID 33149125, 2020). "In addition, it is known that plasma cells produce a variety of pro-osteoclastic factors, such as IL-6, IL-10, Transforming Growth Factor alpha (TGF-α), TGF-β, and matrix metalloproteinases (MMPs), which facilitate the degradation of periodontitis tissues." (PMID 32411181, 2020). "The administration of anakinra to the periodontitis tumor bearing model also had appreciable level of MDSC and some macrophage in the neck area, but the expression of the immune-suppressive cytokines was (IL-2, IL-10, and TGF-ß) was diminished." (PMID 31685946, 2020). "According to TRIPOD29, it was very interesting to test how, although IL10 alone showed non-significant high levels in chronic periodontitis, this acquired an important value within the two-biomarker model, increasing the discriminative capacity of the IL1beta." (PMID 28912468, 2017). "In addition, periodontal ligament cells secrete IL-10, which can be suppressed by IL-1β and it has been hypothesized that periodontal ligament cells can function as accessory immunoinflammatory cells amplifying the inflammatory process in periodontitis, thereby contributing to periodontal breakdown." (PMID 29075409, 2017). "The Th2 cytokines IL10 and IL33 remained unaltered in periodontitis patients." (PMID 27531006, 2016).